RNU2-18P (RNA, U2 small nuclear 18, pseudogene)
Gene: Small nuclear RNA gene on chromosome 10 (16,476,003 to 16,476,164, forward strand). Ensembl gene ENSG00000223156.
Homologues: Orthologues: chimpanzee U2 (81% identical), pig U2 (52% identical), macaque U2 (46% identical), tropical clawed frog U2 (44% identical), dog U2 (39% identical), tropical clawed frog U2 (39% identical), guinea pig U2 (38% identical), rabbit U2 (38% identical), rabbit U2 (37% identical), rat LOC120095483 (35% identical). Paralogues in human: RNU2-2 (65% identical), U2 (65% identical), RNU2-4P (64% identical), U2 (64% identical), RNU2-52P (64% identical), RNU2-48P (62% identical), RNU2-26P (61% identical), RNU2-3P (61% identical), RNU2-57P (61% identical), RNU2-6P (61% identical), RNU2-17P (60% identical), RNU2-61P (60% identical), and 65 more.